NSD3 (nuclear receptor binding SET domain protein 3)
Description:
Histone methyltransferase. Preferentially dimethylates 'Lys-4' and 'Lys-27' of histone H3 forming H3K4me2 and H3K27me2. H3 'Lys-4' methylation represents a specific tag for epigenetic transcriptional activation, while 'Lys-27' is a mark for transcriptional repression.
Synonyms: WHSC1L1; FLJ20353; WHISTLE; KMT3F; KMT3G; pp14328
Tractability: Small molecule: a structure with a bound ligand is known; a high-quality ligand is known; it has a binding pocket of medium quality. PROTAC: UniProt records ubiquitination sites on it; ubiquitination databases record sites on it; a small molecule that binds it is known.
Target class: Writer; Protein methyltransferase; SET domain; Epigenetic regulator
Chemical probes: BI-9321 (high quality)
Gene: Protein-coding gene on chromosome 8 (38,269,704 to 38,382,279, reverse strand). Ensembl gene ENSG00000147548.
Subcellular location: Nucleus; Chromosome
Subcellular location (Human Protein Atlas): Mitochondria; Nucleoplasm
Pathways (Reactome):
Chromatin organization: PKMTs methylate histone lysines
Gene Ontology:
Molecular function: histone H3K27 dimethyltransferase activity; histone H3K27 trimethyltransferase activity; histone H3K36 methyltransferase activity; histone H3K4 dimethyltransferase activity; protein binding; transcription regulator activator activity; histone H3 methyltransferase activity; histone H3K27 methyltransferase activity; histone H3K4 methyltransferase activity; histone methyltransferase activity
Biological process: positive regulation of DNA-templated transcription; regulation of DNA-templated transcription; chromatin remodeling
Cellular component: nucleoplasm; nucleus; chromosome; nuclear lumen
Genetic constraint (gnomAD): Loss-of-function variants: 20 observed, 165.15 expected, observed/expected ratio (o/e) 0.12, 90% interval 0.084 to 0.18. The synonymous counts are far from expectation, so gnomAD's model fits this gene poorly and the ratio says little. Missense variants: 1,140 observed, 1,788.4 expected, observed/expected ratio (o/e) 0.64, 90% interval 0.61 to 0.67. Synonymous variants: 516 observed, 620.85 expected, observed/expected ratio (o/e) 0.83, 90% interval 0.77 to 0.89.
Homologues: Orthologues: chimpanzee NSD3 (99% identical), macaque NSD3 (99% identical), dog NSD3 (96% identical), pig NSD3 (96% identical), guinea pig NSD3 (95% identical), rabbit NSD3 (92% identical), mouse Nsd3 (92% identical), rat Nsd3 (91% identical), tropical clawed frog nsd3 (71% identical), zebrafish nsd3 (60% identical), Caenorhabditis elegans met-1 (12% identical), Drosophila melanogaster Set2 (12% identical), and 11 more. Paralogues in human: NSD2 (43% identical), NSD1 (40% identical), SETD2 (20% identical), ASH1L (15% identical), KMT2A (13% identical), KMT2B (13% identical), KMT2D (12% identical), EZH1 (11% identical), KMT2C (11% identical), EZH2 (11% identical), EHMT1 (11% identical), EHMT2 (10% identical), and 7 more.
Diseases named in the same sentence as NSD3 in open-access papers:
NSD3 is named in the same sentence as 53 diseases in open-access papers, as found by Europe PMC text mining. Sharing a sentence is not in itself a finding about the gene and the disease. The quoted sentences say what the papers report.
breast carcinoma (30 papers, 2014 to 2025). "In patients with breast cancer, high NSD3 expression was associated with elevated PD-L1 levels and reduced CD8+ T cell infiltration." (PMID 41301842, 2025). "NSD3 is located on chromosome 8p11.2, in a region which has been linked to various diseases and that is amplified in primary tumors and cell lines from breast carcinoma." (PMID 34440470, 2021). "While overexpression of NSD3s was able to transform a healthy into a tumorigenic cell, knockdown of NSD3 in 8p11-12–amplified breast cancer cells resulted in loss of growth and survival." (PMID 28903324, 2017). "Collectively, these findings highlight a role for NSD3 in breast tumor progression and suggest that this phenotype might be associated with NSD3-mediated suppression of anti-tumor immunity against breast cancer." (PMID 40586874, 2025). "The WHSC1L1 (Wolf-Hirschhorn syndrome candidate 1-like 1) gene, encoding NSD3, is highly expressed in breast cancer, but its role in the development of breast cancer is still unknown." (PMID 34357103, 2021). "Furthermore, the 8p11.2 region is amplified in breast cancer (BC) and the overexpression of NSD3 is linked to overexpression of the estrogen receptor alpha (ERα) in breast cancer." (PMID 34440470, 2021). "Yang and colleagues (2010) performed the knockdown of the NSD3 expression in breast cancer cell lines and results pointed to a significant loss of growth and survival of employed cell lines, suggesting that NSD3 can act as a probable oncogene, at least in breast cancer." (PMID 32153656, 2020). "NSD3 was initially identified as a gene capable of driving malignant transformation in breast cancer." (PMID 41301842, 2025). "Screening for transforming properties of genes within the 8p11-12 amplicon in breast cancer also suggested that NSD3 functions as a potential oncogene, although the mechanism involving H3K36 methylation remained unclear." (PMID 41301842, 2025). "In human breast cancer, high expression levels of KRT10, HECTD3, NSD3, and STOML2 were associated with unfavorable outcomes, whereas high BTN1A1 expression was linked to a better prognosis." (PMID 40839607, 2025). "NSD3 plays a crucial role in the maintenance of genome integrity, and NSD3 is an important oncogene in breast cancer." (PMID 40839607, 2025). "While, other phosphoproteins (e.g., BTN1A1, KRT10, HECTD3, NSD3, and STOML2) were associated with human breast cancer prognosis." (PMID 40839607, 2025). "In a breast cancer mouse model expressing NSD3 in the mammary epithelium, NSD3 was revealed as a transforming oncogene by exhibiting mammary hyperplasia, dysplasia, and invasiveness." (PMID 38256018, 2024). "NSD3 knockdown decreased proliferation in 8p11-12 amplified breast cancer cell lines, as well as cell cycling in breast, bladder, and lung cancer cell lines, implicating NSD3 in cell cycle regulation." (PMID 36360250, 2022). "Liu and colleagues, in a bioinformatic analysis of breast samples from CBioPortal found that NSD3 is amplified/overexpressed in many subtypes of breast cancer, such as luminal, revealing the behaviour of this gene in different subtypes of breast cancer." (PMID 32153656, 2020). "Next, we investigated how flavopiridol and dinaciclib lead to preferential loss of BRD4/NSD3, impacting the oncogene MYC, thereby, promoting cell cycle arrest in breast cancer." (PMID 32412527, 2020). "Recent studies have identified the Wolf-Hirschhorn syndrome candidate 1-like 1 gene (WHSC1L1, also known as NSD3) as one of the major leader oncogene candidates from the 8p11-12 region in breast cancer." (PMID 28903324, 2017). "NSD3 has been identified as a frequently amplified gene in breast cancer cell lines and primary breast carcinoma." (PMID 28903324, 2017). "The copy number ranges for these genes varied widely, with NSD3/WHSC1L1 amplified at high copy number levels (5–15 copies) in breast cancer patients, while SETDB1 was amplified at 3–6 copy range in melanoma." (PMID 24874471, 2014).
breast carcinoma (continued). "Our previous work identified NSD3 as a driver of metastatic progression in human breast cancer." (PMID 41301842, 2025). "Furthermore, another study analyzed clinicopathologic parameters, immune cell proportions, pathway networks, and in vitro drug responses according to NSD3 expression in various breast cancer datasets." (PMID 40586874, 2025). "NSD3 gene is recurrently amplified at chromosome 8p11.23 in several solid tumors, particularly in breast cancer and lung squamous cell carcinoma, and has recently gained attention as a potent oncogenic driver that promotes tumorigenesis and metastatic progression." (PMID 41301842, 2025). "Notably, NSD3 is located on chromosome 8p11.23, a genomic region recurrently amplified in several solid tumors, including breast cancer and lung squamous cell carcinoma." (PMID 41301842, 2025). "NSD3, as per example is amplified in about 15% of breast cancer." (PMID 32153656, 2020). "Besides, NSD3-induced Methylation of H3K36 could also activate Notch signaling to promote breast cancer initiation and metastasis." (PMID 37415153, 2023). "In addition, the 8p11.2 region is amplified in many cancers, leading to the increased expression of NSD3, and reports have described NSD3 to be essential for tumor maintenance and the suppression of NSD3 expression leads to reduced cell proliferation in lung cancer, breast cancer, and osteosarcoma." (PMID 34440470, 2021). "Furthermore, we demonstrate that NSD3 is a potential prognosis marker for pancreatic cancer, and this finding is consistent with recent studies showing that elevated NSD3 levels are correlated with poor clinical outcome, recurrence, and metastasis in breast cancer." (PMID 37062069, 2023). "NSD3 is located on the chromosome in the 8p11-p12 locus known as Wolf-Hirschhorn syndrome candidate 1-like 1 (WHSC1L1), which is amplified in breast cancer cell lines." (PMID 34357103, 2021). "Frequently affected genes by CNVs in Chinese breast cancer patients were ERBB2 (25%), MIEN1 (25%), GRB7 (24%), TRPS1 (6%), MYC (6%), ERLIN2 (6%), PLPP5 (6%), NSD3 (6%), FGFR1 (6%), and CCND1 (5%)." (PMID 33173047, 2020). "NSD3 is overexpressed in a number of cancers, including breast cancer and lung cancer, but its role in oncogenesis has not been widely investigated." (PMID 24874471, 2014).
lung carcinoma (12 papers, 2014 to 2024). "Overexpression and mutations of the three NSD family members (NSD1, NSD2, and NSD3) have been linked to several types of cancers, including lung cancer, breast cancer, prostate cancer, acute myeloid leukaemia, acute lymphoblastic leukaemia, and multiple myeloma." (PMID 37667522, 2023). "In head and neck squamous cell carcinoma (HNSCC) cells and lung cancer cells, ectopic expression of NSD3-T1232A promoted cancer cell proliferation in vitro and xenograft tumor growth in vivo." (PMID 34615858, 2021). "The endogenous NSD3-s/MYC complexes were also detected in lung cancer H1299 and H1944 cells under physiological conditions by co-immunoprecipitation." (PMID 28205554, 2017). "Knockdown of NSD3 by siRNA in bladder and lung cancer cell lines reduced cell proliferation by inducing cell cycle arrest at G2/M phases through the regulation of the expression of CCNG1 and NEK7, which are important regulators of G2/M transition in cancer cells." (PMID 38256018, 2024). "In blood cancer and lung cancer cells, they could effectively degrade NSD3, inhibit the expression of c-Myc in cancer cells, and affect the growth of cells." (PMID 36770884, 2023). "In addition, NSD3-T1232A expression significantly decreased overall survival in mouse models of lung cancer." (PMID 34615858, 2021). "Both PROTAC were synthesized incorporating an NSD3-PWWP antagonist link to an E3 ligase, showing the degradation of both NSD3 isoforms in cell lines of AML, multiple myeloma, and lung cancer." (PMID 38256018, 2024). "Demonstration of two selected PPIs, MYC/NSD3 and STK11/CDK4, under endogenous conditions in multiple lung cancer cell lines strongly supports the validity of the OncoPPi network data set for further examination." (PMID 28205554, 2017). "BAG4, a protein transcribed from a gene at 8p11.23 with a role in the inhibition of apoptosis, has been shown to transform breast cells and may have functional implications for lung cancer, being commonly coamplified with FGFR1 and NSD3." (PMID 36902501, 2023). "SYL2158 has great selectivity for the degradation of NSD3 and effectively down-regulates the expression of H3K36 methylation and cell proliferation-related genes in lung cancer cells, which is more effective in inhibiting cell growth than NSD3-PWWP antagonist in lung cancer cells." (PMID 36770884, 2023). "With 269 novel interactions, OncoPPi greatly expands the landscape of interactions among this selected set of lung cancer genes and defines interactions with potential significance for cancer PPI target discovery, such as CDK4/STK11, LATS2/RASSF1 and MYC/NSD3 (WHSC1L1)." (PMID 28205554, 2017). "While SETDB1 was recently established as a bona fide amplified cancer driver in melanoma and lung cancer, the role of NSD3/WHSC1L1 has not been well characterized and so we further validated its oncogenic role in vitro (below)." (PMID 24874471, 2014).
lung squamous cell carcinoma (10 papers, 2011 to 2025). "Depletion of NSD3 exhibited tumor growth inhibition in a PDX model of lung squamous cell carcinoma with NSD3-related variants and amplification." (PMID 36911198, 2023). "Specifically, NSD3 amplification occurs in approximately 21% of lung squamous cell carcinomas, 15% of breast invasive carcinomas, and 5% of ovarian serous cystadenocarcinoma cases." (PMID 41301842, 2025). "Elevated histone methylation activity of the histone H3 lysine 36 (H3K36) methyltransferase NSD3 has been related to squamous cell lung cancer." (PMID 37394582, 2023). "Accordingly, NSD3 depletion in patient-derived xenografts from primary lung squamous cell carcinoma samples with NSD3 amplification attenuated tumor growth." (PMID 36360250, 2022). "This work establishes NSD3 as a primary oncogenic driver in lung squamous cell carcinomas with the 8p11-12 amplification." (PMID 36360250, 2022). "Although EGFR L858R mutation was detected throughout the transformation, genomic analyses were performed during the disease course, revealing the amplification of FGFR1 and NSD3, which have recently been proposed as potential driver oncogenes in lung squamous cell carcinoma." (PMID 40792216, 2025). "The variant NSD3 (T1232A) of the methyltransferase NSD3 caused the expression of nearby oncogenes, such as FGFR1, to be turned on by dimethylation of histone H3 lysine 36 (H3K36), which in turn drives the progression of lung squamous cell carcinoma." (PMID 36911198, 2023). "NSD3 has also been identified as an oncogenic driver of lung squamous cell carcinoma." (PMID 36360250, 2022). "Although NSD3 is primarily dysregulated by gene amplification, it also harbors activating mutations within its catalytic SET domain reported in several solid tumors, including head and neck squamous cell carcinoma (HNSCC), lung squamous cell carcinoma (LUSC), and pancreatic cancer cells." (PMID 41301842, 2025). "NSD3 has also been proposed as an oncogenic driver in non-small cell lung cancer (NSCLC), lung squamous cell carcinoma (LUSC) and pancreatic ductal adenocarcinoma (PDAC) where the 8p11-12 amplicon has also been found." (PMID 38256018, 2024). "The histone H3 lysine 36 (H3K36) methyltransferase NSD3, a neighboring gene of FGFR1, has been identified as a critical genetic driver of lung squamous cell carcinoma (LUSC)." (PMID 36291782, 2022). "Ablation of NSD3, but not FGFR1, attenuated tumor growth in a mouse model of lung squamous cell carcinoma." (PMID 36360250, 2022).
acute myeloid leukemia (9 papers, 2015 to 2024). Acute myeloid leukemia (AML) is a group of neoplasms arising from precursor cells committed to the myeloid cell-line differentiation. "Two of the most highly correlated genes with age are OLA1 (encoding the DNA Damage-Regulated Overexpressed on Cancer 45 Protein) and the myelodysplastic syndrome/acute myeloid leukemia-associated gene NSD3." (PMID 30243574, 2018). "This ET domain interacts with a variety of cellular proteins such as histone-lysine N-methyltransferase (NSD3) and Jumonji domain-containing 6 (JMJD6), whose interactions are implicated in acute myeloid leukemia (AML) and various solid tumors, respectively." (PMID 37049806, 2023). "In line with the function of NSD3-short as an adaptor protein of BRD4 and CHD8, MLL-AF9 rearranged acute myeloid leukemia (AML) were proven to be dependent on NSD3." (PMID 34440470, 2021).
NUT carcinoma (9 papers, 2016 to 2025). "Nevertheless, the molecular profile, the NUT::NSD3 gene fusion, has been recurrently described in NUT carcinomas and confirms the diagnosis, especially in association with a squamous phenotype." (PMID 37118352, 2023). "We describe a NUT::NSD3 gene fusion-associated NUT carcinoma of the sinonasal tract with a deceptively well-differentiated papillary growth pattern, thus expanding the morphological spectrum of this typically poorly differentiated neoplasm." (PMID 37118352, 2023). "In NUT midline carcinoma, the NSD3-NUT fusion interacts with BRD4 for BRD4-dependent transcription that is required for blockade of differentiation and sustaining cell proliferation." (PMID 41301842, 2025). "The NSD3::NUTM1 fusion is reported exclusively in NUT carcinoma, an aggressive cancer typically characterized by epithelial differentiation and considered a subtype of squamous cell carcinoma." (PMID 39200173, 2024). "Many fusion partners occur, and NSD3 is NUT carcinoma’s third most common partner." (PMID 39200173, 2024). "WHSC1L1 was also reported to interact with BRD4 through the fusion product WHSC1L1-NUT (NSD3-NUT) observed in a rare squamous cell malignancy known as NUT midline carcinoma, while these cells underwent growth arrest and differentiation upon treatment with the bromodomain inhibitor JQ1." (PMID 27285764, 2016). "Notably, patients with NUT carcinoma in the head and neck region and who exhibit the NSD3::NUTM1 fusion tend to have a notably improved prognosis compared to the typical NUT carcinoma median survival of 6.5 months, with a median overall survival of 36.5 months." (PMID 39200173, 2024). "The typical NUT carcinoma harbors BRD4, BRD3, NSD3, or Z4 bromodomain complex (BDC) protein genes as fusion partners to NUTM1 and manifests histologically as an undifferentiated to poorly differentiated carcinoma." (PMID 34997561, 2022). "Notably, in NUT midline carcinoma, a highly aggressive squamous cell carcinoma characterized by rearrangements of the NUT/NUTM1 gene, a novel NSD3-NUT fusion oncogene has been identified." (PMID 41301842, 2025). "The most common fusion gene partners in NUT carcinoma are BRD4, BRD3, and NSD3." (PMID 39200173, 2024). "Surprisingly, no DEK::AFF2, but a NUT::NSD3 gene fusion was detected, leading to the diagnosis of a NUT carcinoma." (PMID 37118352, 2023). "However, an external histopathological consultation accompanied by molecular work-up with the detection of a NSD3::NUTM1 fusion, yielded the unexpected diagnosis of a sinonasal NUT carcinoma originating from the maxillary sinus." (PMID 37118352, 2023). "One study that included 124 patients of NUT carcinoma found that the mOS of nonthoracic primary NUT carcinoma was significantly better than that of thoracic primary NUT carcinomas, and patients with BRD4-NUT fusion had worse mOS than those with BRD3-NUT or NSD3-NUT fusion." (PMID 34660264, 2021).